MIR599 (microRNA 599)
Synonyms: hsa-mir-599; MIRN599
Gene: MicroRNA gene on chromosome 8 (99,536,636 to 99,536,730, reverse strand). Ensembl gene ENSG00000207804.
Gene Ontology:
Biological process: miRNA-mediated post-transcriptional gene silencing
Homologues: Orthologues: chimpanzee ptr-mir-599 (100% identical), macaque mml-mir-599 (100% identical), dog MIR599 (98% identical), rabbit MIR599 (59% identical).
Diseases named in the same sentence as MIR599 in open-access papers:
MIR599 is named in the same sentence as 2 diseases in open-access papers, as found by Europe PMC text mining. Sharing a sentence is not in itself a finding about the gene and the disease. The quoted sentences say what the papers report.
glioma (1 paper, 2021). A benign or malignant brain and spinal cord tumor that arises from glial cells (astrocytes, oligodendrocytes, ependymal cells). "Yet, MIR599 was reported in two studies to act as a tumor suppressor in glioma tumors, as it was found to be down-regulated." (PMID 34204289, 2021).
MIR599 also shares sentences with these, for which no sentence is quoted: tumor (1 paper).